GCSAML (germinal center associated signaling and motility like)
Synonyms: C1orf150; FLJ44728
Tractability: PROTAC: its protein half-life has been measured.
Gene: Protein-coding gene on chromosome 1 (247,507,058 to 247,577,690, forward strand). Ensembl gene ENSG00000169224.
Subcellular location (Human Protein Atlas): Cytosol
Gene Ontology:
Molecular function: protein binding
Biological process: regulation of B cell receptor signaling pathway; regulation of lymphocyte migration
Genetic constraint (gnomAD): Loss-of-function variants: 6 observed, 5.57 expected, observed/expected ratio (o/e) 1.08, 90% interval 0.58 to 1.83. That is too few expected variants to judge how well the gene tolerates losing a copy. Missense variants: 107 observed, 113.3 expected, observed/expected ratio (o/e) 0.94, 90% interval 0.81 to 1.11. Synonymous variants: 29 observed, 42.38 expected, observed/expected ratio (o/e) 0.68, 90% interval 0.51 to 0.93.
Homologues: Orthologues: chimpanzee GCSAML (99% identical), macaque GCSAML (95% identical), dog GCSAML (69% identical), pig GCSAML (66% identical). Paralogues in human: GCSAM (35% identical).
Diseases named in the same sentence as GCSAML in open-access papers:
GCSAML is named in the same sentence as 5 diseases in open-access papers, as found by Europe PMC text mining. Sharing a sentence is not in itself a finding about the gene and the disease. The quoted sentences say what the papers report.
urticaria (2 papers, 2023 to 2024). A vascular reaction of the skin characterized by erythema and wheal formation due to localized increase of vascular permeability. "The splice-donor variant is consistently the variant at this locus that most significantly associates with urticaria, basophil percentage, platelet count, RNA splicing of GCSAML, and levels of the five mast cell proteins." (PMID 37430141, 2023). "The association of the splice-donor variant in GCSAML with urticaria is thus congruent with the high GCSAML RNA expression seen in human mast cells." (PMID 37430141, 2023). "We found significant trans-pQTL associations of the GCSAML urticaria-associated variant with plasma levels of five proteins encoded by TPSAB1, TPSB2, KIT, SELP, and SIGLEC6 (P-values < 1.0 × 10−7)." (PMID 37430141, 2023). "The most significant urticaria-associated variant, the predicted splice-donor variant at the GCSAML locus, is located at the first base pair of intron 2 in the primary transcript of GCSAML (ENST00000366488.5), disrupting the canonical splice-donor motif (GT becomes AT)." (PMID 37430141, 2023). "Together, these results demonstrate that GCSAML itself is important in the pathogenesis of urticaria." (PMID 37430141, 2023).
cancer (1 paper, 2018). A tumor composed of atypical neoplastic, often pleomorphic cells that invade other tissues. "Thus, the new PARD6G-AS1 and GCSAML imprinted loci undergo cancer-associated epigenetic changes in hematopoietic malignancies." (PMID 29545821, 2018).
hematopoietic cancers (1 paper, 2018). "The methylation statuses at the PARD6G-AS1 and GCSAML iDMRs were perturbed in the methylomes of hematopoietic cancers, with both hypo- and hypermethylated profiles observed in different types of malignancies." (PMID 29545821, 2018). "The maternally inherited 5mCpG imprints at the PARD6G-AS1 and GCSAML iDMRs are perturbed in hematopoietic cancers." (PMID 29545821, 2018).
tumor (1 paper, 2025). "In TCGA-LUAD cohort, the expressions of CHRDL1, P2RX1, GCSAML and APOC4-APOC2 in tumor tissues were significantly lower than those in normal tissues, indicating the tumor-suppressing role of these genes in LUAD." (PMID 40860241, 2025). "Among them, the expression of CHRDL1, P2RX1, GCSAML, and APOC4-APOC2 in the tumor region was significantly lower than that in the normal region." (PMID 40860241, 2025).
GCSAML also shares sentences with these, for which no sentence is quoted: Klinefelter syndrome (1 paper).